RPL3P3 (ribosomal protein L3 pseudogene 3)
Gene: Processed pseudogene on chromosome 14 (56,978,409 to 56,979,621, forward strand). Ensembl gene ENSG00000243388.
Diseases named in the same sentence as RPL3P3 in open-access papers:
RPL3P3 is named in the same sentence as 6 diseases in open-access papers, as found by Europe PMC text mining. Sharing a sentence is not in itself a finding about the gene and the disease.
RPL3P3 shares sentences with these, for which no sentence is quoted: complication (1 paper); deafness (1); diabetic nephropathy (1); diabetic retinopathy (1); genetic disorders (1); hypogonadism (1).